COL4A3 (collagen type IV alpha 3 chain)
Diseases named in the same sentence as COL4A3 in open-access papers (continued):
Sharing a sentence is not in itself a finding about the gene and the disease.
Nephropathy (continued). "With the inclusion of data from previous publications, we collectively studied the molecular genetics of 48 families with collagen IV nephropathies in the Greek population: 12 with defects in the autosomal COL4A3/A4 genes diagnosed with TBMN and 36 AS families of the X-linked mode of inheritance." (PMID 36553470, 2022). "Finally, for the heterozygous COL4A3/COL4A4 pathogenic variants carriers, our data are consistent with a recent systematic review on COL4A3/COL4A4 nephropathy, in which the rate of ESRD is 15.1% at a mean age of 52.8 years." (PMID 33369211, 2021). "COL4A3/COL4A4‐associated TBMN, FSGS and AS may be more appropriate to be classified as collagen IV nephropathies." (PMID 27469977, 2016). "On the other hand, disease-causing variants may be found less frequently in COL4A3 and COL4A4, because these cohorts include individuals with possibly other causes of persistent microscopic haematuria, including IgA, post-streptococcal and C3 nephropathy." (PMID 35260866, 2022). "Therefore, COL4A3/COL4A4‐associated TBMN, FSGS and AS may be better classified as subtypes of collagen IV nephropathies, caused by collagen IV abnormalities, because of the clinical overlap and multiple mutations of the same gene in this group of disorders." (PMID 27469977, 2016). "Further functional studies of the COL4A3/COL4A4 mutations and application of in vitro and/or in vivo models with genetic deficiency are warranted to facilitate a better understanding of the pathogenesis and development of effective treatments for collagen IV nephropathies." (PMID 27469977, 2016). "Given the same genetic lesion, the COL4A3/COL4A4 related FSGS, AS and GBM related diseases should be classified as subtypes of collagen IV nephropathies, which have been encouraged in previous reports." (PMID 33159707, 2020). "It is known that at five weeks of age, Col4a3−/− mice do not show significant kidney damage or elevations in serum levels of phosphate and FGF23." (PMID 39273260, 2024). "We identified two families with thin basement membrane nephropathy caused by a mutation in COL4A3, but no new cases of CFHR5 nephropathy." (PMID 23349874, 2013).
chronic kidney disease (24 papers, 2014 to 2025). Impairment of the renal function secondary to chronic kidney damage persisting for three or more months. "In our study group, both probands with variants in COL4A5 and COL4A3 had a family history of chronic kidney disease." (PMID 40004525, 2025). "In a cohort of adults with chronic kidney disease, COL4A3-5 variants were found in 91 of 3315 (2.7%) individuals." (PMID 39349776, 2025). "In this report, the proband of P11 had a pathogenic variant of COL4A3 gene, and had presentations of chronic renal failure and FSGS." (PMID 38433557, 2024). "All patients had hematuria and/or proteinuria with the exception of only one case (proband 13) that was investigated for dysplastic kidneys and chronic kidney disease, where a variant in COL4A3 was an incidental finding." (PMID 39202375, 2024). "The 129SvJ Col4a3–/– and B6 Col4a3–/– mouse models lack the collagen alpha-3(IV) chain (Col4a3) and display several features of human chronic kidney disease, including progressive loss of kidney function and alterations in bone and mineral metabolism." (PMID 36611094, 2023). "In a first step, a chronic renal disease progression signature was defined using Col4a3-/- mice, which showed proteinuria and progressive loss of renal function." (PMID 34027630, 2021). "In a minority (estimated at 10-20%) of patients with TBMN and heterozygous mutation of COL4A3, 4 or 5 there is progressive renal dysfunction with end stage renal disease (ESRD) in later life, usually after the fifth decade." (PMID 25381091, 2014). "Experimentally, Col4a3-deficient (Col4a3–/–) mice has been an animal model human AS, which develop progressive glomerulonephritis as well as tubulointerstitial scarring and die with end-stage renal disease at an age of approximately 10 weeks." (PMID 31390839, 2019). "The frequencies of proteinuria (75%), family history of MH (75%), hearing loss (50%), chronic kidney disease (41.7%) and use of ACE-I/ ARB (33.3%) were higher in individuals with ARAS compared to individuals with heterozygous COL4A3/A4 variants." (PMID 39349776, 2025). "Historically, it was diagnosed only when significant chronic kidney disease developed; however, more recently, ADAS has been accepted as present when a pathogenic mutation is identified in a COL4A3 or COL4A4 gene." (PMID 41257164, 2025). "As a disease of type IV collagen caused by variants in collagen IV genes (COL4A3, COL4A4, and COL4A5), AS weakens the structural integrity of basement membranes, and leads to chronic kidney disease (CKD), hearing loss, and eye abnormalities." (PMID 40485716, 2025). "We have also implicated infiltrating inflammatory cells and cytokines in the progression of chronic kidney disease in Col4a3-/- mice." (PMID 34502419, 2021). "We have previously implicated tubular epithelial cells, mainly of the proximal tubule and collecting duct, as well as interstitial fibroblasts in the progression of chronic kidney disease in Col4a3-/- mice." (PMID 34502419, 2021). "Chronic kidney disease was observed in none of the individuals with heterozygous COL4A3/A4 variants in our cohort." (PMID 39349776, 2025). "Since patients with heterozygous mutations of COL4A3 or COL4A4 have shown a wide spectrum of disease from TBMN to ADAS, a systematic review has been performed and shown that 29% developed chronic kidney disease (CKD) and 15.1% reached end-stage kidney disease (ESKD)." (PMID 36292665, 2022). "Treatment of Col4a3-/- mice with vorinostat was shown to significantly prolong the lifespan of the animals and exert renoprotective effects, indicating lysine deacetylase inhibition as potential treatment approach for chronic kidney disease." (PMID 34027630, 2021). "Furthermore, in clinically affected patients with heterozygous variants in COL4A3, COL4A4 an increased risk of progression to chronic renal failure was observed in up to 38% and a progression to ESRD was observed in up to 20%." (PMID 29946535, 2018).
chronic kidney disease (continued). "In AS, mutation in the collagen type IV alpha (COL4A) genes Col4A3, A4, or A5 eventually leads to GBM degeneration and consequent proteinuria, inflammation and fibrosis, which are phenotypes that are similar to other chronic kidney diseases (CKD)." (PMID 28873450, 2017).
thin basement membrane nephropathy (19 papers, 2013 to 2025). "About 40–50% of patients with familial microscopic hematuria (FMH) caused by thin basement membrane nephropathy (TBMN) inherit heterozygous mutations in collagen IV genes (COL4A3, COL4A4)." (PMID 29764427, 2018). "Individuals with heterozygous COL4A3 or COL4A4 mutations usually have Thin basement membrane nephropathy with normal renal function but some develop renal impairment." (PMID 27627812, 2016). "Thin basement membrane nephropathy (TBMN) is often attributable to mutations in the COL4A3 or COL4A4 genes that encode the α3 and α4 chains of type IV collagen, respectively, a major structural protein in the glomerular basement membrane." (PMID 26833262, 2016). "A systematic review of 777 thin basement membrane nephropathy/ADAS patients with a single mutation (COL4A3/COL4A4) showed that the prevalence of ESRD in this population was 15.1%, compared to a prevalence of 62% in patients with ARAS and 70% in male patients with XLAS." (PMID 34858896, 2021). "In addition, there were 83 individuals heterozygous for one of these variants, with 70 (84%) heterozygous for p.Gly533Asp in COL4A4 and 13 (16%) for p.Gly139Arg in COL4A3, consistent with the diagnosis of AD AS or thin basement membrane nephropathy." (PMID 36844206, 2023). "The differential diagnosis in 2012 for familial hematuria (FH) includes mostly the COL4A3/A4 heterozygous carriers that exhibit thin basement membrane nephropathy (TBMN) with lifelong microscopic hematuria and a newly described disease, CFHR5 nephropathy, with isolated C3 mesangial deposits." (PMID 23516419, 2013).
glomerular disease (18 papers, 2013 to 2025). "The genes with the highest lifetime risk for monogenic glomerulopathy were COL4A3, followed by COL4A4, CRB2, NPHS1, and NPHS2." (PMID 40677321, 2025). "Although a more precise assessment of the frequency of individuals with a pathogenic variant in COL4A3/COL4A4 is needed, these remain the most common pathogenic variants in genes associated with monogenic glomerular diseases." (PMID 40115110, 2025). "Although FSGS is frequently considered a primary glomerular disease, it can also represent the histological manifestation of genetic disorders affecting the GBM, including mutations in COL4A3, COL4A4 or COL4A5 genes." (PMID 41562995, 2025). "Our study demonstrates that HIM provides nanometer resolution to uncover and rediscover critical ultrastructural characteristics of the glomerulopathy in Col4a3 mutant mice." (PMID 28916834, 2017). "In summary, we established links between abnormal marker expression and GBM disruptions in both primary and secondary glomerular diseases, highlighting the pivotal roles of COL4A3/4/5 and Laminin α5β2γ1 in influencing GBM thickness, alongside perturbations in Integrin α3β1." (PMID 38455522, 2024). "Using Col4A3-deficient mice, they showed the disruptions and progressive disintegration of the GBM-induced vascular leakage from glomerular capillaries into Bowman’s space, which triggers cellular and fibrocellular crescent formation and develops a progressive glomerulopathy." (PMID 39199133, 2024). "Specific deletion of Col4a3 in podocytes (Pod-Crepos; Col4a3L/L) presented with a phenotype similar to the ubiquitous deletion of Col4a3 (CMV-Crepos; Col4a3L/L), with a median survival of 30 wk, significant proteinuria, and histopathological findings associated with glomerular disease." (PMID 38561223, 2024). "Disruptions in the GBM structure and thickness due to aberrant expression of specific molecular markers like COL4A3/4/5, Laminin α5β2γ1 and Integrin α3β1 can lead to GFB dysfunction and, consequently, glomerular diseases." (PMID 38455522, 2024). "COL4A3/4/5 and Laminin α5β2γ1 were identified as pivotal factors influencing GBM thickness, while Integrin α3β1 was found to be perturbed in both types of glomerular diseases." (PMID 38455522, 2024). "In contrast, deletion of Col4a3 in endothelial cells (Cdh5-Crepos; Col4a3L/L) did not result in glomerular disease, with no impact on survival, renal function, and kidney histopathology." (PMID 38561223, 2024).
renal fibrosis (16 papers, 2013 to 2025). A final common manifestation of a wide variety of chronic kidney diseases characterized by glomerulosclerosis and tubulointerstitial fibrosis. "In the COL4A3 knockout mouse, an animal model for AS, it has been shown that parallel to the progression of renal fibrosis at different stages of disease, there is a significant increase in ER-stress proteins, including PDIA3." (PMID 33671535, 2021). "The COL4A3−/−/ITGA2−/− double knockout Alport mouse model has delayed renal fibrosis compared with COL4A3−/−/ITGA2+/+ Alport mice, which express significantly higher levels of MMP2, MMP9, MMP12, and TIMP155." (PMID 29196624, 2017). "Col4a3−/− Alport mice serve as an animal model for renal fibrosis." (PMID 35203245, 2022). "Importantly, the urinary excretion of PDIA3 in the COL4A3 knockout mice correlates with the progression of renal fibrosis in the first 7 weeks." (PMID 33671535, 2021). "Moreover, lack of Ddr1 gene delayed the disease progression in Col4a3-/- AS mouse model, and pharmacological DDR1 inhibition suppressed albuminuria and renal fibrosis in Col4a3-/- mice." (PMID 33706638, 2021). "To elucidate the signaling pathway related to renal fibrosis occurring in the kidneys of Col4a3−/− mice, we performed an immunoblot assay, qPCR, and immunohistochemical staining on the factors involved in the TGF-β/Smad pathway, as a critical mediator of renal fibrosis." (PMID 32144368, 2020).
Microscopic hematuria (13 papers, 2017 to 2025). Microscopic hematuria detected by dipstick or microscopic examination of the urine. "The case at hand is familial microscopic hematuria due to heterozygous disease-causing variants in the COL4A3 or COL4A4 gene, or even the COL4A5 gene (in women), responsible for the X-linked form of AS." (PMID 37761826, 2023). "People who inherit heterozygous COL4A3/A4 variants are at-risk of a slowly progressive form of the disease, starting with microscopic hematuria in early childhood, developing Alport spectrum nephropathy." (PMID 37761826, 2023). "In a cohort of 317 patients with heterozygous deleterious mutations in COL4A3/4, almost 80% of them showed urinalysis alterations (microhematuria, hematuria, and/or proteinuria) before the fourth decade of life." (PMID 36013122, 2022). "There is a relatively high incidence of microhematuria and normal renal function in carriers of deleterious mutations in COL4A3/4." (PMID 36013122, 2022). "In case 1, in a male suspected of AS, genetic testing confirmed the presence of a COL4A3 mutation, which is commonly associated with microhematuria in the first few years of life and slowly progresses to microalbuminuria." (PMID 33305316, 2021). "Pathogenic/likely pathogenic (P/LP) sequence variants in the COL4A3/COL4A4 genes cause a condition that is under-recognized (ranging from completely normal urine sediment to microhematuria, proteinuria and renal insufficiency), poorly understood and not yet well classified." (PMID 38317457, 2024). "In addition to the familiar microscopic hematuria, heterozygous mutations in the COL4A3/A4 present with histological uniform thinning of the GBM, largely known as thin basement membrane nephropathy (TBMN)." (PMID 36553470, 2022). "In addition, COL4A3‐related individuals carrying heterozygous mutations have a vast spectrum of phenotypes, with some showing no symptoms at all and others showing intermittent or permanent microhematuria." (PMID 39924725, 2025). "In one of the largest studies of ADAS, a Spanish cohort involving 82 families and 252 patients with pathogenic COL4A3 or COL4A4 mutations, microscopic hematuria was the most common finding." (PMID 41257164, 2025). "In a report of 53 patients with heterozygous COL4A3/COL4A4 mutations in 25 families, microhematuria, proteinuria (>0.2 g/g⋅Cr), CKD, and ESKD were observed in 100%, 17%, 7.5%, and 5.7% of subjects, respectively." (PMID 36292665, 2022). "In our cohort, among 16 patients with COL4A3 or COL4A4 variants—including those with both genes affected—15 showed microscopic hematuria, all 16 developed proteinuria, and 13 had been noted to have microscopic hematuria during school urinalysis." (PMID 40753325, 2025). "In a systematic review of 777 patients with heterozygous COL4A3/COL4A4 mutations in 258 families, 28.6% of whom received kidney biopsy; microhematuria with/without macrohematuria, proteinuria (>0.5 g/day), CKD, and ESKD were observed in 89.1%, 41.6%, 29%, and 15.1%, respectively." (PMID 36292665, 2022).
diabetic kidney disease (12 papers, 2019 to 2025). Progressive kidney disorder caused by vascular damage to the glomerular capillaries, in patients with diabetes mellitus. "GWAS in patients with diabetic kidney disease/diabetic nephropathy identified a strong association with a variant in COL4A3, a structural component of the glomerular basement membrane." (PMID 33202590, 2020). "For in vivo investigations, they employed db/db mice as a representative model of type 2 diabetes (T2D) accompanied by diabetic kidney disease (DKD), and Col4a3-/- mice as an experimental model for kidney disease linked to Alport syndrome (AS)." (PMID 39114669, 2024). "It has been documented that COL4A3 had a strong signal related to a thinner glomerular basement membrane and protection against albuminuria and diabetic kidney disease." (PMID 38926794, 2024). "Similarly, the COL4A3 rs55703767 is significantly related to protection from diabetic nephropathy." (PMID 38926794, 2024). "In recent years, researchers have conducted more and more large‐scale GWAS and Mendelian randomization analysis to explore the genetic variation related to diabetes nephropathy, including UMOD, COL4A3, COL20A1, TENM2, SLC47A1, and so forth." (PMID 40931579, 2025). "To study the effect of SGLT2i in an experimental model of non-diabetic kidney disease, we developed immortalized podocytes and tubular cell lines established from SV40+; Col4a3+/+ (immorto-WT) and SV40+; Col4a3-/- (immorto-AS) mice." (PMID 37129368, 2023). "Whereas our group previously reported the protective effect of ACE2 replacement in Col4a3–/– mice, the augmentation of circulating ACE2 was not able to delay the development of diabetic nephropathy." (PMID 31390839, 2019).
Hearing impairment (12 papers, 2018 to 2025). A decreased magnitude of the sensory perception of sound. "Consistent with this notion, collagen IV (COL4A3/4/5) variants disrupt BMs and are also associated with hearing impairment." (PMID 35584218, 2022). "Heterozygotes with a pathogenic COL4A3 or COL4A4 variant have hematuria, and sometimes proteinuria, kidney impairment, and hypertension, but they rarely have sensorineural hearing impairment or ocular abnormalities." (PMID 40004525, 2025). "Several collagen genes (COL1A1, COL1A2, COL2A1, COL4A3, COL4A4, COL4A5, COL11A1, and COL11A2) are associated with hereditary syndromic hearing loss." (PMID 33848312, 2021). "Hearing thresholds were gradually increased in Col4a3 KO mice, while the TSA, a HDACi, ameliorated this hearing impairment in AS mice." (PMID 39908276, 2025). "The authors also argue that there is no unmistakable evidence that one mutation in COL4A3 or COL4A4 gene without disease modifying factors can be responsible for the characteristic ultrastructural signs of AS, hearing impairment, or eye abnormalities." (PMID 34212557, 2021).
benign familial hematuria (11 papers, 2015 to 2025). "Mutations in the COL4A3 gene are associated with AS type 3 and benign familial hematuria (MIM#141200) with autosomal dominant inheritance; and with AS type 2 with autosomal recessive inheritance." (PMID 37362409, 2021). "In previous reports of COL4A3 and COL4A4 mutations, the terms "familial benign hematuria (BFH)" and "thin GBM disease" were used." (PMID 38978054, 2024). "COL4A5 mutations are associated with the major X-linked form of the disease, and COL4A3 and COL4A4 mutations are associated with autosomal recessive, dominant forms, and benign familial hematuria." (PMID 30293132, 2019). "NPHS2+/R140Q mice develop no phenotype, while COL4A3+/− mice develop benign familial hematuria." (PMID 30691124, 2019).